ZNF18 (zinc finger protein 18)
Description:
May be involved in transcriptional regulation.
Synonyms: HDSG1; KOX11; ZKSCAN6; ZNF535; Zfp535; ZSCAN38
Tractability: Antibody: the Human Protein Atlas places it where antibodies can reach. PROTAC: ubiquitination databases record sites on it.
Gene: Protein-coding gene on chromosome 17 (11,977,439 to 11,997,475, reverse strand). Ensembl gene ENSG00000154957.
Subcellular location: Nucleus
Subcellular location (Human Protein Atlas): Golgi apparatus; Nucleoplasm; Cytosol; Plasma membrane
Pathways (Reactome):
Gene expression (Transcription): Generic Transcription Pathway
Gene Ontology:
Molecular function: protein binding; DNA-binding transcription factor activity, RNA polymerase II-specific; RNA polymerase II cis-regulatory region sequence-specific DNA binding
Biological process: regulation of transcription by RNA polymerase II; regulation of DNA-templated transcription
Cellular component: nucleus
Genetic constraint (gnomAD): Loss-of-function variants: 41 observed, 57.23 expected, observed/expected ratio (o/e) 0.72, 90% interval 0.56 to 0.93. The upper end of that interval is the gene's LOEUF score, 0.93, which puts it in group 3 of 6, group 1 being the genes least tolerant of losing a copy. Missense variants: 535 observed, 662.96 expected, observed/expected ratio (o/e) 0.81, 90% interval 0.75 to 0.87. Synonymous variants: 230 observed, 249.86 expected, observed/expected ratio (o/e) 0.92, 90% interval 0.83 to 1.03.
Homologues: Orthologues: chimpanzee ZNF18 (99% identical), macaque ZNF18 (97% identical), rabbit ZNF18 (86% identical), dog ZNF18 (82% identical), guinea pig ZNF18 (82% identical), rat Zfp18 (80% identical), mouse Zkscan6 (78% identical), pig ZNF18 (74% identical), Drosophila melanogaster CG12391 (15% identical), Drosophila melanogaster hb (12% identical), zebrafish plagl2 (11% identical), zebrafish ovol1a (11% identical), and 5 more. Paralogues in human: ZSCAN29 (34% identical), ZKSCAN2 (34% identical), ZNF202 (31% identical), ZNF496 (30% identical), ZSCAN32 (30% identical), ZNF274 (28% identical), ZNF446 (24% identical), ZNF174 (22% identical), ZSCAN5B (22% identical), ZSCAN5C (22% identical), ZSCAN5A (21% identical), ZNF444 (18% identical), and 17 more.
Diseases named in the same sentence as ZNF18 in open-access papers:
ZNF18 is named in the same sentence as 7 diseases in open-access papers, as found by Europe PMC text mining. Sharing a sentence is not in itself a finding about the gene and the disease. The quoted sentences say what the papers report.
autism (2 papers, 2019 to 2024). Persistent deficits in social interaction and communication and interaction as well as a markedly restricted repertoire of activity and interest as well as repetitive patterns of behavior. "Genes associated with autism, such as UBE3B and ZNF18, are transcriptionally regulated by membrane depolarization and are involved in experience-dependent learning and synaptic plasticity." (PMID 30867066, 2019). "Additionally, another analysis of the Autism Genetic Research Exchange cohort, consisting of approximately 1,000 multiplex ASD families, identified homozygous and compound heterozygous variants in the ZNF18 gene." (PMID 38830862, 2024).
uterine cancer (1 paper, 2021). Primary or metastatic malignant neoplasm involving the uterine corpus and/or the cervix.
cancer (2 papers, 2022). A tumor composed of atypical neoplastic, often pleomorphic cells that invade other tissues. "Some genes always selected by each method were found (COPS7B, DONSON, GTF2E2, HAUS8, PRH2, and ZNF18) with known roles in cancer formation and progression." (PMID 35954157, 2022). "GEPIA2 database analysis of 33 cancer types showed the following top 10 ALKBH5-related genes: GID4 (R=0.71), TOP3A (R=0.67), MAPK7 (R=0.66), NT5M (R=0.61), FLII (R=0.59), ZNF18 (R=0.57), DRG2 (R=0.57), COPS3 (R=0.56), MED9 (R=0.56) and PRPSAP2 (R=0.56) (all P<0.0001)." (PMID 35444654, 2022).
tumor (1 paper, 2025). "The ZNF (Zinc Finger) family includes TFs such as ZNF18 and ZNF250, which are involved in gene regulation and modulation of tumor cell behavior." (PMID 41155227, 2025).
ZNF18 also shares sentences with these, for which no sentence is quoted: cognitive deficit (1 paper); Renal Cell Cancer (1); schizophrenia (1).